TNF (tumor necrosis factor)
Diseases named in the same sentence as TNF in open-access papers (continued):
Sharing a sentence is not in itself a finding about the gene and the disease.
rheumatoid arthritis (continued). "Also, in a pool of synovial fluid cells from two Rheumatoid Arthritis patients, the immune sera slightly inhibited TNF-α secretion." (PMID 27671547, 2016). "One good model of rheumatoid arthritis is the TNF-α transgenic mouse, in which human TNF-α is overexpressed systemically causing a severe inflammatory and destructive arthritis that starts at 4–8 weeks of age depending on the number of copies of the TNF-α transgene." (PMID 27450561, 2016). "For example, a researcher can run the query above (rheumatoid arthritis and genotyped) and may then want to see how many anti-TNF medications the resulting patients have taken." (PMID 26927184, 2016). "With the present study we wanted to explore the impact of treatment with a tumor necrosis factor-α -inhibitor (TNFi) on levels of soluble biomarkers in rheumatoid arthritis (RA) patients and to identify predictors of impaired drug levels and development of anti-TNFi antibodies (anti-TNFi Abs)." (PMID 27606615, 2016). "Since TNF-α induces protein citrullination in the lung, which is thought to be a potential trigger for rheumatoid arthritis, we hypothesized that TNF-α-induced lung inflammation might induce arthritis development." (PMID 27450561, 2016). "In human rheumatoid arthritis, high levels of TNF-α may be a trigger for the observed citrullination in the rheumatoid lung." (PMID 27450561, 2016). "Similarly, intra-articular delivery of AAV5 vector expressing TNFα antagonist has shown to significantly improve outcome in patients with rheumatoid arthritis." (PMID 27070581, 2016). "Besides anti-drug antibodies, anti-nuclear antibodies and anti-DNA antibodies are often induced in patients with rheumatoid arthritis treated with tumor necrosis factor inhibitors." (PMID 27643491, 2016). "Moreover, in the treatment of rheumatoid arthritis, several drugs have been used; among the most common are the biologic disease-modifying antirheumatic drugs (bDMARD) or TNF-α inhibitors." (PMID 27294919, 2016). "Anti-TNF-α drugs are used in rheumatoid arthritis and Crohn’s disease/Ulcerative colitis patients." (PMID 26870037, 2016). "Given the presence of arthritis as well as both airway disease and interstitial lung disease (both of which have links to rheumatoid arthritis) induced by TNF-α, this model is particularly useful for exploring the pathophysiology of rheumatoid arthritis and rheumatoid lung disease." (PMID 27450561, 2016). "Concomitantly, TNF is a major player of the inflammatory response, as illustrated by successful therapeutic strategies targeting TNF in patho logies such as Crohn’s diseases, rheumatoid arthritis or psoriasis." (PMID 26071594, 2015). "Clinical disease activity and systemic inflammation are independent predictors of mortality from cardiovascular disease (CVD) in rheumatoid arthritis (RA), and studies have shown that methotrexate and tumour necrosis factor-α inhibitors (TNF-α) therapy can reduce CVD mortality." (PMID 26114946, 2015). "In agreement with this hypothesis, inhibition of Sirt1 enzymatic activity reduces LPS-induced levels of TNF in monocytes of patients with rheumatoid arthritis." (PMID 25799392, 2015). "Real-time qPCR was performed using whole blood RNA samples obtained from seventy-five rheumatoid arthritis patients about to commence treatment with a TNF inhibitor biologic drug, whose response status was determined at 3-month follow-up using the EULAR classification criteria." (PMID 26667261, 2015). "According to a recent systematic review based on 23 studies, TNF-α inhibitors were convincingly shown to prevent or even reverse the progression of intima media thickness in patients with rheumatoid arthritis, ankylosing spondylitis and psoriatic arthritis who respond to treatment." (PMID 26633680, 2015).
rheumatoid arthritis (continued). "Equivalent efficacy and onset of action of abatacept and anti-TNF therapy have also been demonstrated in patients with an inadequate response to MTX in the Abatacept versus adaliMumab comParison in bioLogic-naïvE rheumatoid arthritis subjects with background methotrexate (AMPLE) trial." (PMID 28936386, 2015). "Considering that rheumatoid arthritis is a chronic disease, antioxidant properties allied to TNF-α and CCL2 inhibition might be beneficial for inflammation resolution." (PMID 25878716, 2015). "In addition, the use of a TNF-α neutralizing antibody ameliorated insulin resistance in patients with rheumatoid arthritis." (PMID 26413130, 2015). "Furthermore, arterial stiffness was improved in patients with rheumatoid arthritis treated with TNF-α inhibitors." (PMID 26504819, 2015). "Similarly, a previous study from our group of 107 Korean patients with either rheumatoid arthritis or ankylosing spondylitis who received TNF-α antagonist therapy and were followed up for 13–33.5 months found that no patients developed active TB." (PMID 26474294, 2015). "Notably, treatment of rheumatoid arthritis subjects with TNF-α-antibodies restores Treg function, decreases PP1 expression, and increases FOXP3 phosphorylation." (PMID 25741338, 2015). "Interestingly, when the concentration of 4-HNE increased to 50 μM, the mRNA levels of IL1-β, IL-6, and TNF-α in rheumatoid arthritis synovial cells increased gradually with the increasing time up to 1 h and then decreased." (PMID 25741130, 2015). "Anti-TNF-α therapy in rheumatoid arthritis patients reduces aortic PWV." (PMID 25807386, 2015). "TNF is the major cytokine driving inflammation in rheumatoid arthritis (RA), a chronic inflammatory disease affecting about 1% of the world's population and characterized by synovial inflammation and joint destruction, leading to severe morbidity and premature mortality." (PMID 26287732, 2015). "The aim of this study was to survey factors related to EULAR good response, the DAS-28 definition of remission, ACR 50 response, sustained response to tumor necrosis factor inhibitors (TNF-I) therapy in biologic naïve patients with refractory rheumatoid arthritis." (PMID 25977895, 2015). "But so far, only contrary studies exist, demonstrating either beneficial or no beneficial effects of an anti-TNFα therapy on the cardiovascular risk of rheumatoid arthritis patients." (PMID 26076475, 2015). "TNF-α is the major therapeutic target for rheumatoid arthritis." (PMID 26000303, 2015). "Anti-TNF-α is used to improve bone metabolism in patients with rheumatoid arthritis." (PMID 26199898, 2015). "TNF is a potent pro-inflammatory factor and of primary importance in pathogenesis of rheumatoid arthritis, and the inhibition of TNF could suppress various arthritis models while overexpression of TNF could induce spontaneous erosive inflammatory arthritis." (PMID 25602164, 2015). "Furthermore, three months of TNF-α inhibitory drug treatment has been shown to significantly raise cEPCs in rheumatoid arthritis patients." (PMID 26044827, 2015). "TNF-α, an inflammatory cytokine released by activated monocytes, macrophages, and T lymphocytes, promotes inflammatory responses that are important in the pathogenesis of rheumatoid arthritis." (PMID 23986016, 2014). "Our results demonstrate that 5-LOX is involved in TNF-α-induced inflammatory arthritis and may provide a new strategy for treating rheumatoid arthritis." (PMID 25229347, 2014). "TNF-α has been documented to be of major importance in the pathogenesis of rheumatoid arthritis." (PMID 25501574, 2014). "Pathomechanistically one could speculate at this stage that an inhibitory effect of Adalimumab on bone turnover might be mediated by a reduction of RANKL which could already be shown in patients with rheumatoid arthritis and anti-TNF-α therapy." (PMID 24400722, 2014).
rheumatoid arthritis (continued). "Moreover, nicotine inhibits TNF-α-induced IL-6 and IL-8 secretion in fibroblast-like synoviocytes from patients with rheumatoid arthritis." (PMID 25479074, 2014). "However, other studies performed with TNFα antagonists on subjects with rheumatoid arthritis and ankylosing spondylitis reveal different results (improvement and no change), but not an increase in insulin resistance." (PMID 25392783, 2014). "TNFα plays a central role in the pathogenesis of rheumatoid arthritis (RA)." (PMID 24593170, 2014). "There have only been a few case reports of Salmonella septic arthritis in a rheumatoid arthritis patient on anti–tumor necrosis factor treatment but none previously in association with certolizumab." (PMID 26425605, 2014). "TNFα inhibitors are already common in the therapy of rheumatoid arthritis." (PMID 25207597, 2014). "Decision makers could give greater weight to the TNF inhibitors because of fairness considerations: patients with rheumatoid arthritis represent the worse off group of the two." (PMID 25089121, 2014). "We crossed TNFα-overexpressing mice, which develop a chronic inflammatory, erosive arthritis similar to rheumatoid arthritis, with FAKf/f mice, in which the fak gene is floxed, and Rosa26-CreERT2 mice, in which Cre recombinase deletes floxed genes upon exposure to tamoxifen." (PMID 25280866, 2014). "The aim of the present study was to explore the use of high frequency color Doppler ultrasound to measure synovial thickness and blood flow to assess the therapeutic value of the recombinant human tumor necrosis factor (TNF) II receptor antibody fusion protein in rheumatoid arthritis (RA) treatment." (PMID 25371736, 2014). "Homozygous FCGR3A-V/V158 individuals have since been found to have improved biological responses to anti-CD20 therapy in immune thrombocytopenia and rheumatoid arthritis (RA); and anti-TNF-α therapy (Infliximab) to treat Crohn’s disease; compared to carriers of one or two FCGR3A-F158 alleles." (PMID 24910634, 2014). "Infliximab, an anti-TNF-α monoclonal antibody, is effective in treating rheumatoid arthritis." (PMID 24587984, 2014). "Güler-Yüksel’s study have found that treatment with TNF-α inhibitor might reduce hand OA in patients with rheumatoid arthritis, which shed light to the role of anti-TNF-α in treatment of hand OA." (PMID 25398219, 2014). "Furthermore, it was subsequently revealed that a number of rheumatoid arthritis patients treated with anti-TNF therapy developed neurological symptoms, including demyelinating lesions." (PMID 24587232, 2014). "The level of TNFα in the synovial fluid in rheumatoid arthritis (RA) is high." (PMID 25037855, 2014). "Monoclonal antibodies targeting TNF- α in rheumatoid arthritis suggests that similar approaches using cytokine or cytokine receptor antagonists, or using suppressive cytokines may be successful in the treatment of HT." (PMID 25506398, 2014). "Patients with rheumatoid arthritis have high concentrations of TNF-α in their synovial fluid." (PMID 23986016, 2014). "Rheumatoid arthritis patients receiving TNF-α blockers were reported to become infected with Pneumocystis carinii, Legionella pneumophila, M. tuberculosis, Echinococcus multilocularis, Histoplasma capsulatum, non-typhi Salmonella, and non-tuberculous mycobacteria." (PMID 25329064, 2014). "The distribution of TNF-α expression in PsA is similar to that described in rheumatoid arthritis although this cytokine levels in the psoriatic form may be somewhat greater than in RA." (PMID 24676037, 2014). "The soluble forms of the receptors have been reported to act as physiological attenuators of TNF-α activity, where the shedding of TNF-Rs leads to diminished surface receptors and this process has been proposed to reduce the clinical activity resulting from TNF-α in rheumatoid arthritis." (PMID 24457057, 2014).
rheumatoid arthritis (continued). "Indeed there are several clinical trials using different p38 inhibitors to treat patients with various illnesses, including acute lung toxicity and rheumatoid arthritis, where TNF-α plays a major role." (PMID 23468959, 2013). "In clinics, pharmacological blockade of TNFα activity – i.e., by the neutralizing antibody infliximab or the soluble TNFαR Etanercept – used to reduce symptoms of rheumatoid arthritis or Crohn’s disease, has been since few years ago extended also to IMs, although some caution has been recommended." (PMID 24204948, 2013). "Therefore, the anti-TNF-α drugs are highly effective treatment for chronic inflammatory diseases such as rheumatoid arthritis and Crohn’s disease." (PMID 23738990, 2013). "The majority of data from the international research shows that abatacept is both clinically efficient and highly cost effective in the treatment of moderate to severe rheumatoid arthritis, especially in patients that have demonstrated inadequate response or intolerance to anti-TNF agents or DMARDs." (PMID 23819062, 2013). "Thus, drugs that selectively target TNF-α in activated mast cells and basophils are promising therapeutic candidates for rheumatoid arthritis and Crohn's disease." (PMID 24349023, 2013). "TNF-α may play a key role in bone metabolism and is important in inflammatory bone diseases such as rheumatoid arthritis." (PMID 23762085, 2013). "The CD4+CD28- lymphocytes are suggested to acquire their phenotype in relation to increased proinflammatory state of the individual (notably increased levels of TNF), and themselves participate in inflammatory processes including rheumatoid arthritis, chronic kidney disease and atherogenesis." (PMID 23835405, 2013). "Reactivation of latent tuberculosis (TB) after therapeutic tumor necrosis factor (TNF) blockade during chronic inflammatory diseases such as rheumatoid arthritis highlights TNF as an essential mediator containment of infection with Mycobacterium tuberculosis (Mtb)." (PMID 23460846, 2013). "In diseases such as OA and rheumatoid arthritis (RA) chondrocytes are targeted, via specific cell-surface cytokine receptors, by pro-inflammatory cytokines such as interleukin-1β (IL-1β) and tumour necrosis factor-α (TNF-α)." (PMID 24373218, 2013). "Peripherally targeted opioids may be used in a co-treatment approach with other therapies (e.g., cytokine modulators or TNF-α antagonists) at low doses for conditions such as rheumatoid arthritis." (PMID 24167491, 2013). "Our results demonstrate that Nec-1 modulates TNF-induced proinflammatory response, and may potentially be used as a therapeutic target for inflammatory diseases such as rheumatoid arthritis and osteoarthritis." (PMID 24199619, 2013). "This group of diseases, which is also referred to as TRECID (TNF-α related chronic inflammatory diseases), includes psoriasis as well as Crohn’s disease, rheumatoid arthritis, and in current discussions maybe also PG." (PMID 24010984, 2013). "Notably, the chronic aberration in the baseline levels of TNF in human circulatory system has been attributed to the pathogenesis of numerous diseases, including rheumatoid arthritis, osteoporosis, sepsis and cancer." (PMID 24199619, 2013). "In humans, TNF-α has been implicated in the physiopathology of autoimmune diseases and consequently anti-TNF-α treatments (antibodies or soluble receptor) have been used with successful results obtained in Crohn’s disease and rheumatoid arthritis." (PMID 23801992, 2013). "The gene TNFA, which encodes the proinflammatory cytokine TNF-α, is located in the MHC region on chromosome 6 and has been implicated in susceptibility to a number of rheumatic diseases, including rheumatoid arthritis." (PMID 24160187, 2013). "Indeed, the field of rheumatoid arthritis has been aggressive in adopting immunomodulatory biologic agents including TNFα inhibitors, T-cell costimulation suppressors, and B-cell depleting antibodies to ameliorate inflammatory disease." (PMID 24278766, 2013).
rheumatoid arthritis (continued). "Importantly there was also potential for participants to confuse information relating to anti-TNF with information from previous counselling sessions for other rheumatoid arthritis medications over the years." (PMID 23663548, 2013). "Neutralization therapies using the soluble TNF receptor-2-IgG-Fc fusion protein, etanercept, or anti-TNF-α monoclonal antibodies such as infliximab have proved to be a successful strategy for ameliorating both inflammation and joint destruction in rheumatoid arthritis." (PMID 23762085, 2013). "In addition to these classical available therapies, there are several reports regarding the use of disease-modifying antirheumatic drugs (DMARDs) and anti-TNF therapy, which act as potentially effective therapies for rheumatoid arthritis." (PMID 23971039, 2013). "Our results suggest that, as in rheumatoid arthritis, the IL-1β- and TNF-α-rich pannus-like tissue may be an invasive tissue involved in the progression of knee osteoarthritis." (PMID 24223987, 2013). "In agreement with this hypothesis, inhibition of Sirt1 enzymatic activity reduces LPS-induced levels of TNFα in monocytes of patients with rheumatoid arthritis." (PMID 23844973, 2013). "Latent Mtb infection also poses iatrogenic clinical challenges, due to increases in TB reactivation following administration of biologicals, such as tumor necrosis factor-alpha (TNFα)/IL-12/IL-23 blockers in treating inflammatory diseases like rheumatoid arthritis, Crohn's disease, and psoriasis." (PMID 22589713, 2012). "Several autoimmune diseases, including rheumatoid arthritis (RA) and psoriasis, had been considered to be Th1-cell-mediated disorders driven by a population of T cells producing inflammatory cytokines, such as IL-2, IL-12, TNF-α and interferons." (PMID 22359594, 2012). "Rheumatoid arthritis (RA) is a chronic autoimmune disease associated with production of elevated levels of pro-inflammatory cytokines, including IL-12, IL-6, IL-1, IL-23, and TNFα, that are involved in activation of naïve T cells and directing their polarization into TH1 and TH17 cells." (PMID 22969767, 2012). "We hypothesised that fatigue in rheumatoid arthritis (RA) is related to TNF-alpha induced dysregulation of cerebral blood flow." (PMID 23211089, 2012). "The goal of this study is to investigate whether the -308G > A promoter polymorphism in the tumor necrosis factor alpha (TNFA) gene is associated with disease severity and radiologic joint damage in a large cohort of patients with rheumatoid arthritis (RA)." (PMID 23217265, 2012). "Medications used to treat rheumatoid arthritis, such as corticosteroids, disease-modifying agents (DMARDs), and injectable biological agents (anti-TNFα), may have widespread effects on wound healing." (PMID 23251815, 2012). "TNF-α also mediates many inflammatory events in rheumatoid arthritis, including immune cell activation, proliferation, apoptosis and regulation of leukocyte movement, which has led to the development of strategies to block TNF-α-mediated effects." (PMID 23056531, 2012). "The risk of LTBI reactivation is further increased by the treatment with tumour-necrosis-factor-α- (TNFα-) blocking agents, which have been proven to be effective therapy in autoimmune conditions such as rheumatoid arthritis (RA), psoriasis and psoriasis arthritis (PsA), and ankylosing spondylitis." (PMID 22666260, 2012). "In contrast to the clinical utility of anti-TNF therapies in rheumatoid arthritis but worsening of symptoms when anti-TNF is used in most other autoimmune diseases, these experiments have repeatedly shown that TNF or TNF-inducers protect against onset and progression of many forms of autoimmunity." (PMID 22905105, 2012). "The efficacy of TNF-blocking agents was lower in Dutch Rheumatoid Arthritis Monitoring registrants." (PMID 21624184, 2011).